FANCI (FA complementation group I)
Diseases named in the same sentence as FANCI in open-access papers (continued):
Sharing a sentence is not in itself a finding about the gene and the disease.
infection (4 papers, 2022 to 2026). The state of being infected such as from the introduction of a foreign agent such as serum, vaccine, antigenic substance or organism. "The combined depletion of USP1–PCNA/FANCD2/FANCI in WT infection triggered a robust increase in inversions and deletions across the entire CMV genome (lightest blue bars) relative to the siNTC." (PMID 41533576, 2026). "By contrast, in ∆UL138STOP infection, SNV counts increased in the USP1–PCNA/FANCD2/FANCI knockdown relative to any other knockdown in ∆UL138STOP infection." (PMID 41533576, 2026). "Only 25% of the novel junctions arising from depletion of USP1–PCNA/FANCD2/FANCI overlap with ∆UL138STOP infections, suggesting an important role for UL138 in directing these pathways." (PMID 41533576, 2026). "Further, depletion of USP1–PCNA/FANCD2/FANCI was sufficient to compromise viral genome integrity in WT infection." (PMID 41533576, 2026). "In our study, following siRNA infection, the wound healing assay results indicated that the migration speed slowed after FANCI was knocked down." (PMID 40417238, 2025). "To gain more insight into the role of UL138 and USP1–PCNA/FANCD2/FANCI in controlling DDR pathways and maintaining CMV genome integrity, we analyzed the distribution and type (e.g. inversions, deletions, or duplications) of structural variants in each of our infection and knockdown conditions." (PMID 41533576, 2026). "By contrast, the rearrangements in the UL region arising in UL138-mutant infection occurred independently of repeat sequences and USP1–PCNA/FANCD2/FANCI." (PMID 41533576, 2026). "Compared to NTC, depletion of PCNA/FANCD2/FANCI or PCNA/FANCD2/FANCI combined with USP1 increased viral genome synthesis in WT and ∆UL138STOP infections." (PMID 41533576, 2026). "Finally, we were intrigued by finding that depletion of USP1–PCNA/FANCD2/FANCI did not increase junctions beyond the disruption of UL138 in infection." (PMID 41533576, 2026). "BRCA1, BRCA2, FANCI, and FANCD2 were substantially downregulated following WT-H. pylori infection, but not upon infection with the ΔcagA H. pylori strain, highlighting the CagA-dependence in their downregulation." (PMID 35163588, 2022).
genetic disease (2 papers, 2021). "FA is a heterogenous genetic disease with 22 known causal genes, where FANCI implicated cases comprise approximately 1% of all FA diagnoses." (PMID 34861889, 2021).
FANCI also shares sentences with these, for which no sentence is quoted: pancreatic cancer (4 papers); acute myeloid leukemia (3); osteosarcoma (3); sarcoma (3); medulloblastoma (2); microphthalmia (2); Pan (2); rectal cancer (2); adrenocortical cancer (1); Amoebiasis (1); ascending colon cancer (1); attention deficit-hyperactivity disorder (1); Azoospermia (1); benign tumors (1); bladder urothelial carcinomas (1); Bloom syndrome (1); brain tumors (1); breast tumors (1); cervical squamous cell carcinoma (1); Ewing sarcoma (1); familial colorectal cancer (1); familial prostate carcinoma (1); Fanconi anemia complementation group I (1); gallbladder cancer (1); HCMV infection (1); head and neck carcinoma (1); Hepatitis B (1); invasive carcinoma (1); leukopenia (1); Li-Fraumeni syndrome (1).
A further 17 diseases each share a sentence with FANCI in 1 paper.